BRCA1 (BRCA1 DNA repair associated)
Diseases named in the same sentence as BRCA1 in open-access papers (continued):
Sharing a sentence is not in itself a finding about the gene and the disease.
ovarian carcinoma (continued). "Two previous studies have examined the relationship between BRCA1 protein expression and prognosis in ovarian carcinomas." (PMID 19602291, 2009). "Increases in aromatase and its proximal promoter I.3/II transcripts were also observed in these BRCA1 mutation carriers, supporting the hypothesis that with decreased BRCA1 function there is a dysregulation of aromatase transcription regulation and a predisposing factor to breast and ovarian cancer." (PMID 19445691, 2009). "Peritoneal carcinomas were less likely to have low BRCA1 protein than ovarian carcinomas (p = 0.049, Fishers Exact, two-tailed)." (PMID 19602291, 2009). "According to previously published results, this mutation accounts for 31% of the BRCA1 and BRCA2 mutations identified in Greek familial breast/ovarian cancer patients." (PMID 19491894, 2009). "Germline mutations in the BRCA1 and BRCA2 (BRCA1/2) tumor suppressor genes are highly penetrant for increased risks of breast and ovarian cancers." (PMID 19277124, 2009). "Our data combined with these two previous studies confirm an improved prognosis for women with advanced ovarian carcinomas with low BRCA1 protein expression." (PMID 19602291, 2009). "These authors have shown that inhibition of BRCA1 expression in ovarian cancer cell lines increases cell sensitivity to platinum derivatives, while reduces the antitumor activity of taxanes." (PMID 19825178, 2009). "Our data suggest that ovarian carcinomas maintain the coordinate regulation of BRCA1 and BRCA2 seen in normal tissues." (PMID 19602291, 2009). "Our data are consistent with previous reports that BRCA1 promoter methylation occurs in 5–20% of sporadic ovarian carcinomas." (PMID 19602291, 2009). "The most advanced case is the PARP-1 inhibitors, on their own or in combination with DNA-damaging chemotherapeutics, which are in phase-II clinical trials with breast/ovarian cancer patients having BRCA1/BRCA2 null tumours." (PMID 19319136, 2009). "In this study BRCA1, BRCA2 and CHEK2*(1100delC) were analyzed for mutations in 91 HBOC/HBC/HOC families and early onset breast and early onset ovarian cancer cases." (PMID 19656415, 2009). "BRCA1 and BRCA2 are the two most frequently mutated genes underlying inherited breast and ovarian cancer." (PMID 18298804, 2008). "Approximately 5% to 10% of ovarian cancers are familial and in most families affected with breast and ovarian cancer a genetic linkage has been established with the BRCA1 locus." (PMID 18721484, 2008). "Germline inactivating mutations in BRCA1 and BRCA2 underlie a major proportion of the inherited predisposition to breast and ovarian cancer." (PMID 18298804, 2008). "As part of the model fitting, we have also re-estimated the breast and ovarian cancer risks in BRCA1 and BRCA2 carriers." (PMID 18349832, 2008). "Germline mutations in BRCA1 and BRCA2 cause an increased lifetime risk for breast and ovarian cancer." (PMID 18501021, 2008). "Women with BRCA1 or BRCA2 mutations have a substantially increased risk of breast and ovarian cancer compared with the general population." (PMID 18410690, 2008). "BRCA1 and BRCA2 mutations account for an important fraction of hereditary breast and ovarian cancer cases." (PMID 18489799, 2008). "Germline and somatic mutations, loss of heterozygosity (LOH), and epigenetic events such as promoter hypermethylation can lead to decreased expression of BRCA1/2 in ovarian cancers." (PMID 18208621, 2008). "The discovery of the BRCA1 and BRCA2 genes has transformed the management of women who are at high risk of developing breast and ovarian cancer." (PMID 18627636, 2008). "We evaluated 49 ovarian carcinomas and categorized them according to pathology and BRCA1 and BRCA2 status." (PMID 18208621, 2008). "BRCA1 and BRCA2 are the two major susceptibility genes, accounting for varying fraction of familial breast and ovarian cancer cases in different populations." (PMID 18501021, 2008).
ovarian carcinoma (continued). "Since the identification of the BRCA1 and BRCA2 genes a great deal of debate has focussed on the issue of breast and ovarian cancer risk associated with mutations in these genes." (PMID 18513387, 2008). "We identified one large deletion in BRCA1, deleting the most part of the gene (exon 1A-13) in one family with family history of ovarian cancer." (PMID 18501021, 2008). "Women with BRCA1 or BRCA2 mutation have a substantially increased risk of breast and ovarian cancer compared with the general population." (PMID 18410690, 2008). "BRCA1 and BRCA2 are the two most important genes associated with familial breast and ovarian cancer susceptibility." (PMID 18501021, 2008). "The BOADICEA model can be used to estimate the likelihood of carrying a BRCA1 or a BRCA2 mutation, and the risks of developing breast or ovarian cancer." (PMID 18349832, 2008). "Despite annual gynaecological screening, a high proportion of ovarian cancers in BRCA1/2 carriers are interval cancers and the large majority of all cancers are diagnosed in advanced stages." (PMID 17426707, 2007). "Original estimates of breast and ovarian cancer risks in carriers were based on the families used for positional cloning of the BRCA1 and BRCA2 genes, where all carriers had molecular testing, and all cancer diagnoses were validated." (PMID 17213823, 2007). "We chose SKOV-3 cells as a cellular model for ovarian cancer because in these cells the BRCA1 and BRCA2 genes, which are located next to the LASP-1 gene on chromosome 17q21, are upregulated." (PMID 17211471, 2007). "Among the remaining 883 BRCA1/2 carriers 10 women (all BRCA1) were diagnosed with ovarian cancer during follow-up (incident cases)." (PMID 17426707, 2007). "BRCA1 and BRCA2 mutations increase breast and ovarian cancer risks substantially enough to warrant risk reduction surgery, despite variable risk estimates." (PMID 17213823, 2007). "We apply our methods to incorporate oophorectomy into the BRCAPRO model, which predicts a woman's risk of carrying mutations in BRCA1 and BRCA2 based on her family history of breast and ovarian cancer." (PMID 17378937, 2007). "The purpose of this study was to determine the type and frequency of large genomic rearrangements in the BRCA1 gene in hereditary breast and ovarian cancer cases in the Czech Republic." (PMID 17561994, 2007). "Germline mutations in BRCA1 (OMIM#113705, Online Mendelian Inheritance in Man) and BRCA2 (OMIM#600185) genes are responsible for an important fraction of hereditary breast and ovarian cancers." (PMID 17561994, 2007). "The functional interaction between the DNA helicase BRIP1 and the breast/ovarian cancer susceptibility gene BRCA1 makes common variants in BRIP1 good candidates for low to moderate penetrance susceptibility to both breast and ovarian cancer." (PMID 17342202, 2007). "In this study, we examined the chemosensitivity under suppression of endogenous BRCA1 expression using BRCA1-specific siRNA in ovarian cancer cell lines." (PMID 19690636, 2007). "Mutations in BRCA1 gene (and BRCA2) are associated with inherited breast and ovarian cancer, although the exact nature of this tissue specificity is incompletely understood." (PMID 17850658, 2007). "BRCA1 and BRCA2 were identified as genes mutated in hereditary breast/ovarian cancer by genetic analysis in families with multiple cases of these malignancies." (PMID 17213823, 2007). "Women carrying a germline heterozygous mutation in either BRCA1 or BRCA2 are predisposed to breast and ovarian cancer." (PMID 17324252, 2007).
ovarian carcinoma (continued). "BRCA1 and BRCA2 are critical to prevent breast and ovarian cancers in mutation carriers but the proteins participate in processes that are fundamental for survival in other types of cells." (PMID 17683622, 2007). "It is located on chromosome 17q22, just distal to the BRCA1 gene located at 17q21, a region that is frequently somatically altered in both breast and ovarian cancer." (PMID 17342202, 2007). "Our results showed that the sensitivity to cisplatin was significantly increased by BRCA1 suppression in A2780 ovarian cancer cells." (PMID 19690636, 2007). "The emerging picture is that breast and ovarian cancer risks in BRCA1 and BRCA2 carriers are substantially higher than in the general population, but that they are considerably affected by nongenetic, environmental factors, and by additional genetic modifiers." (PMID 17213823, 2007). "In summary, here we propose a fast, flexible and cost-effective multiplex assay of the ten most frequent BRCA1 and BRCA2 mutations in Spain, for the initial screening of Spanish and Spanish ancestry population's breast/ovarian cancer families." (PMID 17603881, 2007). "BRCA-1 and BRCA-2 mutation carriers often participate in a surveillance programme for early detection of ovarian cancer consisting of annual pelvic examination and transvaginal ultrasound (TVU) combined with serum CA-125 assessment." (PMID 16495917, 2006). "BRCA1 and BRCA2 mutation carriers are at increased risk for developing both breast and ovarian cancer." (PMID 16563180, 2006). "BRCA1 expression is repressed through promoter hypermethylation in 11–31% of breast, 5–15% of ovarian cancer and about 60% of pancreatic ductal carcinoma." (PMID 17047656, 2006). "Founder mutations in both BRCA1 and BRCA2 genes have been characterized in French-Canadian high-risk breast/ovarian cancer families." (PMID 16417652, 2006). "Specific methylation was found in cervical cancer (including CDH1, DAPK, MGMT and MINT2), endometrial cancer (CASP8, CDH13, hMLH1 and p73), and ovarian cancer (BRCA1, p14, p15, RIZ1 and TMS1)." (PMID 16928264, 2006). "A number of models that predict BRCA1 and BRCA2 mutation carrier risks and/or breast and ovarian cancer risks have been reported in the literature." (PMID 16417652, 2006). "Germline mutations in the BRCA1 and BRCA2 genes have been shown to account for the majority of hereditary breast and ovarian cancers." (PMID 16168118, 2005). "It is estimated that 5% to 10% of cancer is caused by autosomal dominant inherited genetic changes, such as BRCA1 and BRCA2 mutations in breast and ovarian cancer." (PMID 15888219, 2005).
ovarian carcinoma (continued). "Women with a BRCA1 or BRCA2 germline mutation are at an increased risk of developing breast and ovarian cancer." (PMID 15083174, 2004). "The discovery of the BRCA1 and BRCA2 genes has induced widespread interest in genetic testing for inherited susceptibility of breast and ovarian cancer." (PMID 14735173, 2004). "Mutations in the 5′-end of BRCA1 and BRCA2 were associated with a significantly increased risk for ovarian cancer relative to the central portion of the gene." (PMID 15026808, 2004). "Since the efficiency of these screenings methods is still not clear, prophylactic surgery of the ovaries for patients with proven BRCA1 or BRCA2 mutations or a strong family history of breast and/or ovarian cancer is an important option." (PMID 15083174, 2004). "At the time of salpingo-oophorectomy, five of 58 BRCA1 carriers (8.6%) were diagnosed with an occult carcinoma: two fallopian tube carcinomas, two ovarian carcinomas and one case was defined as a fallopian tube/ovarian carcinoma." (PMID 15083174, 2004). "Germ line mutations in the BRCA1 and BRCA2 genes predispose individuals to breast and ovarian cancer." (PMID 15353005, 2004). "Following the identification of two predisposition genes (BRCA1 and BRCA2) that increase the risk of breast and/or ovarian cancer, there has been a gradual introduction of genetic testing into the clinical context." (PMID 15505627, 2004). "The predicted prevalences of BRCA1 and BRCA2 mutations among unselected cases of breast and ovarian cancer are also consistent with observations from population-based studies." (PMID 15381934, 2004). "More precise penetrance estimates have been derived in a meta-analysis of the families of BRCA1/2 carriers identified through population-based studies of breast and ovarian cancer." (PMID 15381934, 2004). "For the other family with two mutations (BRCA1 and BRCA2), it has been possible to identify the separate routes of inheritance and hence to calculate the numbers of breast and ovarian cancers attributable to each mutation." (PMID 12698193, 2003). "Individual women with both breast and ovarian cancer were recorded in 36% of BRCA1 families, with up to three instances per family, whereas they occurred in only 10% of BRCA2 families and no family included more than one case." (PMID 12698193, 2003). "The ratio of breast to ovarian cancers is 2.39 : 1 for BRCA1 families and 6.18 : 1 for BRCA2 families, a difference which is significant at the 0.01% level by χ2 analysis." (PMID 12698193, 2003). "It has been shown that upregulation of BRCA1 expression leads to increased resistance to CDDP in ovarian cancer cells." (PMID 12698198, 2003). "We also allowed for separate ovarian cancer relative risks in the age groups 30–49, 50–59, and 60–69 years for BRCA1 and in the age groups 30–49 and 50–69 years for BRCA2." (PMID 11857015, 2002). "The relative risks of breast and ovarian cancer in BRCA1 and BRCA2 carriers, relative to the BCLC risks were all estimated to be less than one." (PMID 11857015, 2002). "Unique germline mutations in BRCA1 and BRCA2 account for inherited predisposition to breast and ovarian cancer in high-risk families." (PMID 9667663, 1998). "In this trial, women aged 25 - 55 years with BRCA1 variants, no history of breast or ovarian cancer, and no plans for prophylactic breast surgery are randomized to receive either denosumab 120 mg subcutaneously or placebo every 6 months for 5 years." (PMID 41488281, 2026). "In one study from Poland, 1,814 women with BRCA1 pathogenic variants, with no prior ovarian cancers, and intact ovaries underwent at least one screening transvaginal ultrasound." (PMID 41488281, 2026). "It has been reported that individuals carrying a BRCA1 (BReast CAncer gene 1) gene mutation have a significantly higher risk of developing ovarian cancer compared to those without the mutation." (PMID 41614943, 2026).
ovarian carcinoma (continued). "Furthermore, BRCA1 and BRCA2, which are causative genes for hereditary breast and ovarian cancers, have each been detected in 1% of patients, and PALB2, BRIP1, NBN, and RAD51D were detected in 3% overall." (PMID 41214301, 2026). "Endometrial cytology may play a role as a potential surveillance tool for women with BRCA1/2 gPV, even at early stages of ovarian cancer." (PMID 41692918, 2026). "Mutations in the BRCA1 and BRCA2 genes play a significant role in ovarian cancer pathogenesis." (PMID 41493488, 2026). "Mutations in BRCA1 and BRCA2 genes are the leading cause of hereditary breast and ovarian cancer." (PMID 40543584, 2025). "While patients with hereditary breast and ovarian cancer with germline double heterozygosity (GDH) for BRCA1 and BRCA2 are rare, carcinogenesis in these cases remains unclear." (PMID 40601170, 2025). "Patients with ovarian cancer with high levels of BRCA1 hypermethylation are very likely to have high genomic instability scores, which may sensitize tumors to PARPi treatment." (PMID 40075848, 2025). "In humans, mutations in BRCA1 and BRCA2 predispose individuals to breast and ovarian cancer." (PMID 40852952, 2025). "First, the baseline characteristics lack some confounding factors for ovarian cancer, such as BRCA1/2 pathological mutant status, which might influence the outcome." (PMID 40622947, 2025). "Several tumor suppressors and genome stability proteins are now understood to suppress R-loops: for example, BRCA1 and BRCA2 (breast/ovarian cancer suppressors) help resolve R-loops at stalled forks and DSB sites, and loss of BRCA1 leads to R-loop accumulation and replication stress." (PMID 40332372, 2025). "Frontline PARP inhibitor maintenance therapy provides a substantial PFS benefit for newly diagnosed epithelial ovarian cancer patients with BRCA pathogenic variants, with the most pronounced efficacy observed in mutations located within the DNA-binding domains of BRCA1 and BRCA2." (PMID 40075604, 2025). "Additionally, genetic mutations, particularly in the BRCA1 and BRCA2 genes, significantly increase the risk of ovarian cancer." (PMID 40896438, 2025). "As of January 2022, niraparib has been included on the list of reimbursed drugs (in Poland) for the indication of ovarian cancer without mutations in the BRCA1/2 genes." (PMID 40429755, 2025). "Mutations found in Australian women with a strong history of breast and ovarian cancer but not BRCA1 or BRCA2 mutation are located in the MM1 domain, and appear essential for FANCF binding." (PMID 40447800, 2025). "BRCA1- and BRCA2-associated hereditary breast and ovarian cancer (HBOC) is characterized by an increased risk for male and female BC, ovarian cancer (including fallopian tube and primary peritoneal cancers), and, to a lesser extent, other cancers, such as prostate, pancreatic, and melanoma." (PMID 40648909, 2025). "Since both parents of the proband were healthy at the age of 73 and given the high prevalence of pathogenic variants in the BRCA1 and BRCA2 genes in ovarian cancer, as well as their significant therapeutic implications, the initial molecular analysis focused on these two genes." (PMID 40076915, 2025). "It has been speculated that a large portion of the uterine and cervical cancers found in BRCA1/2 GPV carriers could be misdiagnosed ovarian cancers." (PMID 40427184, 2025). "Some well-established nLTR-derived examples include de novo Alu insertions into BRCA1 and BRCA2, which predispose carriers to hereditary breast and ovarian cancers, and germline L1 insertions into the APC TSG, which underlie familial adenomatous polyposis and increase colorectal cancer risk." (PMID 40950107, 2025). "BRCA1 and BRCA2 mutations were identified as ovarian cancer risk factors." (PMID 40869932, 2025).